MEX3A (mex-3 RNA binding family member A)
Description:
RNA binding protein, may be involved in post-transcriptional regulatory mechanisms.
Synonyms: RKHD4; RNF162; MEX-3A
Tractability: PROTAC: ubiquitination databases record sites on it; its protein half-life has been measured.
Gene: Protein-coding gene on chromosome 1 (156,072,013 to 156,082,465, reverse strand). Ensembl gene ENSG00000254726.
Subcellular location: Cytoplasm; Nucleus; Cytoplasm, P-body
Subcellular location (Human Protein Atlas): Cytosol
Gene Ontology:
Molecular function: RNA binding; nucleic acid binding
Cellular component: cytosol; P-body; cytoplasm; nucleus
Genetic constraint (gnomAD): Loss-of-function variants: 4 observed, 24.68 expected, observed/expected ratio (o/e) 0.16, 90% interval 0.079 to 0.37. The upper end of that interval is the gene's LOEUF score, 0.37, which puts it in group 1 of 6, group 1 being the genes least tolerant of losing a copy. Missense variants: 457 observed, 633.8 expected, observed/expected ratio (o/e) 0.72, 90% interval 0.67 to 0.78. Synonymous variants: 287 observed, 278.23 expected, observed/expected ratio (o/e) 1.03, 90% interval 0.94 to 1.14.
Homologues: Orthologues: chimpanzee MEX3A (100% identical), macaque MEX3A (99% identical), pig MEX3A (99% identical), rat Mex3a (98% identical), dog MEX3A (97% identical), mouse Mex3a (97% identical), guinea pig MEX3A (87% identical), tropical clawed frog mex3a (68% identical), Drosophila melanogaster CG11360 (39% identical), Caenorhabditis elegans mex-3 (31% identical). Paralogues in human: MEX3B (49% identical), MEX3D (47% identical), MEX3C (43% identical).
Diseases named in the same sentence as MEX3A in open-access papers:
MEX3A is named in the same sentence as 50 diseases in open-access papers, as found by Europe PMC text mining. Sharing a sentence is not in itself a finding about the gene and the disease. The quoted sentences say what the papers report.
colorectal cancer (18 papers, 2017 to 2026). A primary or metastatic malignant neoplasm that affects the colon or rectum. "In colorectal cancer, high expression of Mex-3 RNA-binding family member A (MEX3A) is associated with poor prognosis." (PMID 40642070, 2025). "In particular, the protein dysregulation of MEX3A was significantly associated with a variety of human malignant tumors, such as in gastric cancer, colorectal cancer, bladder cancer, and pancreatic ductal adenocarcinoma." (PMID 33827584, 2021). "In terms of direct targets, SMYD2 regulates the level of H3K36me2 on Mex-3 RNA-binding family member A (MEX3A), thereby controlling the growth of colorectal cancer by regulating the target of MEX3A, namely, caudal type homeobox 2 (CDX2)." (PMID 39482529, 2024). "Recently, the dysregulation of MEX3A has been described in several types of human cancers, such as gastric carcinoma, glioma and colorectal cancer." (PMID 37433992, 2023). "Many studies have indicated that MEX3A promotes cell proliferation and inhibits cell apoptosis in bladder cancer, gastric cancer, and colorectal cancer." (PMID 36507941, 2023). "Further, MEX3A plays complex and diverse roles in the development of various malignancies, including colorectal cancer, lung cancer, liver cancer, cervical cancer, and glioma." (PMID 35490173, 2022). "Many studies have pointed out that MEX3A is involved in mRNA regulation and influences the development of various diseases, especially human cancers, such as gastric cancer, bladder cancer, colorectal cancer, liver cancer, and glioblastoma." (PMID 35433464, 2022). "Several studies reported that MEX3A promoted the cancer progression of lung cancer, colorectal cancer, and ovarian cancer through the regulation of the mRNA expression of its target genes." (PMID 36614043, 2022). "Supporting the role of MEX3A in radioresistance of colorectal cancer cells, it has been reported that the upstream regulator E2F3 functions on DNA damage response." (PMID 36276637, 2022). "Till now, the role of MEX3A has been elucidated in several types of human cancer including gastric cancer, colorectal cancer and nephroblastoma." (PMID 33188661, 2020). "Yang utilized the Azoxymethane/Dextran sodium sulfate (AOM/DSS) mouse model to investigate the role of Mex-3 RNA Binding Family Member A (MEX3A) in colorectal cancer, while Clements employed piggyBac transposition and CRISPR-Cas9-mediated somatic glioblastoma mouse models for further exploration." (PMID 39204153, 2024). "However, the functions of Mex-3 RNA binding family member A (MEX3A) in colorectal cancer (CRC) metastasis remain poorly understood." (PMID 38914858, 2024). "We then sought to examine conservation of MEX3A / KLF4 relationship in human colorectal cancer." (PMID 36276637, 2022). "Recently, MEX3A has been reported as a novel biomarker promoting proliferation and migration in various cancers such as pancreatic ductal adenocarcinoma (PDA), liver cancer, and colorectal cancer; yet, its role in OC is still unclear." (PMID 34189143, 2021). "Whether these cancer stem cells are able to upregulate Lgr5 expression in a BMAL1 independent manner and how BMAL1, MEX3A and Lgr5 regulatory relationship in colorectal cancer stem cells differs from that in non-cancerous intestinal tissue will also be of interest for further investigation." (PMID 37845346, 2023).
breast carcinoma (15 papers, 2020 to 2025). "This higher expression of MEX3A was linked with the poor survival of breast cancer." (PMID 34486491, 2021). "We further found that higher levels of MEX3A were expressed in various kinds of tumors (e.g., ovarian cancer, lung cancer, breast cancer, etc.)in comparison to normal tissues, and MEX3A in EC was significantly upregulated (p < 0.05)." (PMID 36614043, 2022). "In the present study, not only was MEX3A highly expressed in different molecular subtypes of breast cancer, but also the expression was significantly different among the four different molecular subtypes, indicating the specificity of MEX3A expression." (PMID 35433464, 2022). "Our study found that MEX3A expression level was much higher in human breast cancer tissues as compared to adjacent normal tissues." (PMID 34486491, 2021). "Abnormal activation of MEX3A can promote tumor cell proliferation, metastasis, and migration in gastric cancer and pancreatic ductal adenocarcinoma, breast cancer, and osteosarcoma." (PMID 34189143, 2021). "Firstly, we used GEPIA and KM-plotter databases to evaluate MEX3A expression in human breast cancer tissue compared to adjacent normal tissue." (PMID 34486491, 2021). "In summary, these data indicate that MEX3A can enhance RhoA/ROCK1/LIMK1 signaling in breast cancer cells." (PMID 34486491, 2021). "Overall, our study concluded that MEX3A promotes its migration and proliferation in breast cancer cells via modulating RhoA/ROCK1/LIMK1 signaling pathway." (PMID 34486491, 2021). "This study to designed to evaluate the expression of MEX3A in human breast cancer tissues and cell lines." (PMID 34486491, 2021). "Due to MEX3A’s established links with regulation of both EMT and proliferation of intestinal and various types of cancer cells, we knocked down MEX3A in ER- BT-20, CAL-148 and HCC1187 breast cancer cells to determine if MEX3A regulates similar processes." (PMID 32909943, 2020). "Both distant metastasis-free survival and overall survival of breast cancer patients are reduced when high levels of MEX3A are expressed in primary tumours, as would be expected for a SOX11 target." (PMID 32909943, 2020). "We found many SOX11+ breast cancer cell lines express high levels of MEX3A or TUBB3 compared to DCIS.com cell line." (PMID 32909943, 2020). "(H) Pie charts representing the percentage of breast cancer samples with a log2 fold-change greater than two in the levels of MEX3A or TUBB3 RNA when SOX11 increased between 0.5- and 2-fold, 2- and 4-fold, or greater than 4-fold in the TCGA dataset." (PMID 32909943, 2020). "Interestingly, it has been shown that MEX3A regulates the Wnt pathway by downregulating Dickkopf WNT signaling pathway inhibitor 1 (DKK1) expression in breast cancer." (PMID 38914858, 2024). "However, the role and deep-going regulatory mechanism of MEX3A in breast cancer still require further elucidation." (PMID 37433992, 2023). "And, MEX3A promote the malignant progression of breast cancer by directly targeting IGFBP4 mRNA." (PMID 37433992, 2023). "Therefore, this research aimed to study how MEX3A regulates the biological behaviors of breast cancer." (PMID 34486491, 2021). "This study demonstrated that MEX3A expression is increased in breast cancer." (PMID 34486491, 2021). "This upregulation of MEX3A accelerates the proliferation and migration of breast cancer cells." (PMID 34486491, 2021). "Therefore, we designed this study to evaluate the expression of MEX3A in human breast cancer tissues and cell lines." (PMID 34486491, 2021). "Moreover, inhibition of MEX3A decreased cell proliferation and migration in breast cancer cell lines." (PMID 34486491, 2021). "Moreover, we found that overexpression of MEX3A stimulated proliferation and migration in the breast cancer cells." (PMID 34486491, 2021). "In this study, MEX3A expression in breast cancer is upregulated." (PMID 34486491, 2021).
breast carcinoma (continued). "Similarly, breast cancer cell lines showed higher expression of MEX3A as compared to the normal breast cells." (PMID 34486491, 2021). "However, inhibition of MEX3A significantly reduced the proliferation and migration of breast cancer cells." (PMID 34486491, 2021). "Expression of two potential downstream effectors of SOX11 signalling we recently identified in breast cancers cells, Mex3a and Rcor2, which have links to stem cell proliferation and reprogramming, respectively, were also substantially reduced in Brca1.3 cells with reduced Sox11 levels." (PMID 33969421, 2021). "Finally, we assessed the MEX3A dependent regulation of RhoA/ROCK1/LIMK1 signaling pathway involved in the progression of breast cancer." (PMID 34486491, 2021). "However, in mouse models of breast cancer, MEX3A upregulation was induced by SOX11, a member of the SOXC transcription factors, consisting of SOX4, SOX11 and SOX12." (PMID 34067172, 2021). "Also, the phosphorylation of RhoA, ROCK1 and LIMK1 in breast cancer cells is positively regulated by MEX3A." (PMID 34486491, 2021). "Despite epigenetic alterations like altered methylation pattern, as proposed for MEX3A in the context of breast cancer, genomic instability events come progressively in the focus of cancer biology, as chromosomal alterations are prominent in nearly all cancers and serve as the hallmark of cancer." (PMID 34067172, 2021). "Similarly, MEX3A mRNA expression level in breast cancer tissues was significantly higher, in contrast to adjacent normal tissues." (PMID 34486491, 2021). "MEX3A showed low expression in breast cancer patients with long survival, which may be related to methylation modifications." (PMID 33080569, 2020). "In line with other studies, MEX3A expression increased in breast cancer patients." (PMID 33080569, 2020). "Despite of these studies, the relationship between MEX3A and breast cancer is still unclear." (PMID 33188661, 2020). "Knockdown of MEX3A significantly inhibited breast cancer cell proliferation, migration, and invasion by promoting IGFBP4 expression, revealing the regulatory mechanism of MEX3A targeting IGFBP4 in BC cells." (PMID 37433992, 2023). "Therefore, we suggest that MEX3A may be a potential target for personalized treatment for different molecular subtypes of breast cancer." (PMID 35433464, 2022). "Therefore, we investigated whether MEX3A affected RhoA/ROCK1/LIMK1 signaling in breast cancer cells." (PMID 34486491, 2021). "Therefore, we speculate that MEX3A promotes the progression of breast cancer through RhoA/ROCK1/LIMK signaling pathway." (PMID 34486491, 2021). "Furthermore, MEX3A can regulate RhoA/ROCK1/LIMK signaling pathway in breast cancer cells." (PMID 34486491, 2021). "For example, MEX3A may act as a tumor promoter for breast cancer by regulating PIK3CA." (PMID 34189143, 2021). "In addition, we determined that MEX3A could activate RhoA/ROCK1/LIMK1 signaling in the breast cancer cells." (PMID 34486491, 2021). "Thus, in breast cancer cells, MEX3A can facilitate their proliferation and migration." (PMID 34486491, 2021). "Therefore, MEX3A modulates the activity of RhoA/ROCK1 signaling in breast cancer." (PMID 34486491, 2021). "Moreover, we also aimed to determine the functions of MEX3A in breast cancer cells." (PMID 34486491, 2021). "In our study, we confirmed that MEX3A, as a novel RBP, was significantly correlated with the proliferation, metastasis and prognosis of breast cancer." (PMID 37433992, 2023). "The results showed that FBN2, MEX3A, and TPD52 were highly expressed in luminal A, luminal B, HER2-enriched, and basal-like breast cancers compared with normal samples." (PMID 35433464, 2022). "Their expression and prognosis in the four types of breast cancer were observed separately, and the results showed that FBN2, MEX3A, and TPD52 were more expressed in luminal A, HER2, and TPD52 than in normal samples." (PMID 35433464, 2022).
breast carcinoma (continued). "The target genes of miR-139-5p were predicted by using an online database TargetScan and miRDB, and three key genes, FBN2, MEX3A, and TPD52, were screened in combination with differentially expressed genes in different molecular subtypes of breast cancer." (PMID 35433464, 2022). "A total of three key genes were obtained after overlapping the predicted target genes with the differentially upregulated genes in the four types of breast cancer: FBN2, MEX3A, and TPD52." (PMID 35433464, 2022). "Human bone marrow mesenchymal stem cell-derived exosomes inhibited the growth of breast cancer cells and promoted the expression of FBN2, MEX3A, and TPD52 by transporting miR-139-5p." (PMID 35433464, 2022). "Thus, MEX3A may promote the carcinogenesis and development of breast cancer." (PMID 34486491, 2021). "MEX3A, a novel SOX11 downstream effector, regulates cell growth and (E/M) state of ER- breast cancer cells." (PMID 32909943, 2020). "Analysis of GSE37754 methylation data showed that the methylation levels of MEX3A and TBC1D 9 were negatively correlated with the mRNA expression levels in breast cancer." (PMID 33080569, 2020). "Together, these results are consistent with roles for MEX3A in regulation of cell growth and EMT in SOX11+ ER- breast cancer cells." (PMID 32909943, 2020). "In addition, the key target genes of miR-139-5p, FBN2, MEX3A, and TPD52 also provide potential targets for personalized treatment of different molecular subtypes of breast cancer." (PMID 35433464, 2022). "In the human breast cancer cell line MCF10DCIS.com, MEX3A and MEX3B could be identified among the 25 most upregulated targets due to SOX11 overexpression." (PMID 34067172, 2021). "Overall, our research indicates that MEX3A and RhoA/ROCK1/LIMK signaling may be new targets for breast cancer treatment." (PMID 34486491, 2021). "MEX3A and TBC1D 9 were methylated and affected the prognosis of breast cancer." (PMID 33080569, 2020). "Thus, MEX3A and TBC1D 9 are affected by methylation in breast cancer survival." (PMID 33080569, 2020). "However, MEX3A dependent regulation of breast cancer has not been fully elucidated." (PMID 34486491, 2021).
gastric cancer (15 papers, 2017 to 2023). A primary or metastatic malignant neoplasm involving the stomach. "Concerning the functional relevance of MEX-3A expression, its downregulation in gastric cancer cell lines caused a reduced cell proliferation, migration, and transformation capacity." (PMID 32717840, 2020). "At the same time, the migration of cells was significantly inhibited by the knockdown of MEX3A in gastric cancer cells." (PMID 33414423, 2021). "The significantly upregulated expression in gastric cancer tissues compared with normal tissues also indicated MEX3A as a participant in development and progression of gastric cancer." (PMID 33188661, 2020). "MEX3A is known to be upregulated in Wilms renal cancer, gastric cancer, bladder cancer and bladder urothelial cancer." (PMID 31998552, 2020). "Recent studies have reported that Mex3a is overexpressed in cancers like bladder urothelial carcinoma and Wilm’s tumor meanwhile Mex3a gene is closely related to the proliferation, apoptosis, and metastasis of gastric cancer cells." (PMID 32792503, 2020). "MEX3A mRNA was recently shown to be overexpressed in Wilms tumors, gastric cancer, bladder cancer, and bladder urothelial carcinoma." (PMID 31998552, 2020). "Recently, it has been reported that knockdown of Mex3A by siRNAs inhibits cell proliferation and migration in human gastric cancer cells." (PMID 28977858, 2017). "Furthermore, knockdown of MEX3A by small RNA interference suppressed cell proliferation and migration in human gastric cancer cells." (PMID 33827584, 2021). "In gastric cancer, suppressing MEX3A inhibits cellular proliferation and migration." (PMID 34486491, 2021). "On the other hand, MEX3A expression was significantly upregulated in gastric cancer tissues relative to normal tissues, indicating MEX3A as a participant in development and progression of gastric cancer." (PMID 33414423, 2021). "In addition, wound healing assay and Transwell assays showed that MEX3A knockdown significantly inhibited the migration of gastric cancer cells." (PMID 33188661, 2020). "Previous studies have shown that mex3a promoted cell division and metastasis and might be a hazard factor in gastric cancer and Wilms tumors." (PMID 28903380, 2017). "Previous studies have shown that Mex3a regulates CDX2 in human colon cancer and promoted proliferation in gastric cancer and glioblastoma." (PMID 32792503, 2020). "In addition to such TCGA data, a study reported higher expression levels of MEX-3A mRNA levels in human gastric cancer tissues, compared to matched, adjacent, non-cancer tissues, suggesting that human MEX-3A is involved in the development and metastasis formation of this disease." (PMID 32717840, 2020).